CTLA4 (cytotoxic T-lymphocyte associated protein 4)
Diseases named in the same sentence as CTLA4 in open-access papers (continued):
Sharing a sentence is not in itself a finding about the gene and the disease.
small cell lung carcinoma (23 papers, 2016 to 2025). Small cell lung cancer (SCLC) is a highly aggressive malignant neoplasm, accounting for 10-15% of lung cancer cases, characterized byrapid growth, and early metastasis. "Immune checkpoint inhibitors (CPIs) including anti-programmed cell death 1 (PD-1), anti-PD ligand 1 (PD-L1) and anti-cytotoxic lymphocyte associated protein 4 (CTLA-4) antibodies have shown promising results in several solid cancers including small cell lung cancers." (PMID 29986769, 2018). "The aim of this study is to explore cytotoxic T lymphocyte associated antigen 4 (CTLA-4), programmed death 1 (PD-1) and programmed death ligand 1 (PD-L1) distribution and clinical value in liquid biopsy (such as blood) of small cell lung cancer (SCLC) patients." (PMID 29167005, 2017). "Immune checkpoint blockade (ICB) targeting the PD-1/PD-L1 axis or CTLA-4 has a very limited effect on patients with small cell lung cancer (SCLC), the most aggressive form of lung cancer." (PMID 38533509, 2024). "All relevant articles are identified by using the keywords “small cell lung cancer,” “SCLC,” “immunotherapy,” “CTLA-4,” “PD-1,” “PD-L1,” “clinical trial” on Pubmed, clinicaltrials.gov, Embase and Web of science." (PMID 34136376, 2021). "Another case of a female patient with small-cell lung cancer (SCLC), treated with an anti-CTLA-4/PD-1 combination therapy, was reported." (PMID 30547012, 2018). "For example, combinations of CTLA-4 and PD-1 inhibitors have been investigated in patients with NSCLC and small cell lung cancer (SCLC)." (PMID 27938382, 2016). "Compared to PD-1/PD-L1 inhibitors, CTLA-4 inhibitors were weak in treating small cell lung cancer with high side effects, which may be the reason why there were fewer RCTs of CTLA inhibitors for small cell lung cancer." (PMID 38319920, 2024).
kidney transplant (22 papers, 2012 to 2025). A surgical procedure in which one or both kidneys from a donor are implanted into a recipient. "Belatacept, a CTLA4-Ig, was designed to prevent rejection and graft loss in kidney transplant recipients." (PMID 38001955, 2023). "Contrasting results exist on the association between CTLA-4 rs231775 and acute rejection in kidney transplant recipients." (PMID 32732985, 2020). "CTLA-4 expression was associated with longer OS in lymph node-positive patients (OS: HR: 0.53 (0.31–0.92); P=0.021) but not in lymph node-negative patients (HR: 0.51 (0.20–1.29); P=0.14)." (PMID 32602545, 2020). "In conclusion, CTLA4 haplotype ACGG was partially associated with the development of DILI in Chinese kidney transplant recipients." (PMID 23300559, 2012). "In conclusion, the CTLA4 haplotype ACGG was partially associated with the development of DILI in Chinese kidney transplant recipients." (PMID 23300559, 2012). "In conclusion, the CTLA4 genotype rs231775 AA may be one of risk factors for the development of malignancy in Chinese kidney transplant recipients." (PMID 25667935, 2015). "CTLA4‐Ig has been approved by the Food and Drug Administration for immunosuppressive therapy in kidney transplantation." (PMID 40292672, 2025). "In regard to belatacept, a second-generation form of CTLA4-Ig/ABT used for kidney transplant recipients, the efficacy of a third vaccine dose for humoral response is controversial." (PMID 36569794, 2023). "Similar to our findings, found that the CTLA4 rs4553808 genotype significantly affected the postoperative TAC concentration in Chinese kidney transplant patients." (PMID 36457704, 2022). "In its proper use (prevention of kidney transplant rejection), immunosuppressant Nulojix® (belatacept, CTLA-4) is a very expensive therapy." (PMID 31950032, 2019). "The high-affinity CTLA4-Ig, belatacept, currently approved for use in kidney transplant recipients inhibits CD28 costimulation, a critical pathway for Tconv cell activation as well as Treg cell development and homeostasis." (PMID 29973932, 2018). "Overall, these results show a poor overall response rate when the treatment criteria are based on breast cancer receptor subtypes and the expression of PD-1/PD-L1 and CTLA4, stressing the need for new criteria and more reliable biomarkers." (PMID 30513096, 2018). "In addition, the combination of ICOS blockade with the inhibition of other checkpoints, such as CTLA-4, seems to be particularly effective in generating anti-tumor responses in prostate preclinical models." (PMID 40427227, 2025). "Nevertheless, large studies comprising Asian or African kidney transplant recipients are still required to clarify the impact of CTLA-4 rs231775 on acute rejection risk in non-Caucasian populations." (PMID 32732985, 2020). "Next, we investigated whether blocking the CD28-B7 co-stimulation pathway using CTLA-4 Ig, a fusion protein currently used as maintenance therapy in kidney transplant recipients, in combination with IL2c would also promote allograft survival in our model." (PMID 28484450, 2017). "Our data show that the CTLA4 genotype rs231775 AA may be one of risk factors for the development of malignancy and haplotype TACAG was susceptible haplotype in Chinese kidney transplant recipients." (PMID 25667935, 2015). "Although the activation and expansion of T cells through the lack of negative regulation by PD-1 and CTLA-4 are considered the immune pathogenesis of irAEs, the molecular mechanisms underlying the development of liver irAE remain unclear." (PMID 41200202, 2025). "Following evaluation of the BENEFIT trials, Belatacept, a high-affinity version of CTLA4-Ig, has been FDA approved for use in kidney transplant recipients." (PMID 36119093, 2022). "This updated systematic review and meta-analysis, which included a total of 5,401 kidney transplant recipients, showed that CTLA-4 rs231775 is not a genetic determinant of acute rejection." (PMID 32732985, 2020).
celiac disease (21 papers, 2009 to 2026). An autoimmune genetic disorder with an unknown pattern of inheritance that primarily affects the digestive tract. "Multiple genes have been implicated in the pathogenesis of celiac disease, particularly HLA-DQ and CTLA-4." (PMID 39727645, 2024). "It is approximated that 59% of patients with heterogenous germline mutations of CTLA-4 presented with gastrointestinal manifestations, such as diarrhea with malnutrition, pancreatic insufficiency, atrophic gastritis, CD, and celiac disease." (PMID 36612082, 2022). "In contrast, earlier studies have shown that CTLA4 (rs4675374-A) is a risk factor for celiac disease (OR = 1.14)." (PMID 27015091, 2016). "Patients who develop ICI-induced celiac disease may have a variant of celiac disease with cross-tolerance and decreased penetrance that is unrestricted by the blockade of CTLA-4." (PMID 39727645, 2024). "Variations in CTLA-4 have been implicated in many autoimmune conditions, including celiac disease." (PMID 39727645, 2024). "In addition, AD and celiac disease may share a similar genetic background, as polymorphisms of the CTLA4 gene have been linked to both conditions." (PMID 38256267, 2024). "According to one study, untreated patients with celiac disease had high cytotoxic T lymphocyte antigen-4 (CTLA-4) concentrations in their serum." (PMID 39727645, 2024). "In our study, the effects of pure gliadin on the level of pro-inflammatory cytokines and the expression level of CTLA-4 in people with celiac disease and healthy people were evaluated." (PMID 38040898, 2023). "Both of these variants, especially CTLA-4 CT60, are associated with autoimmune diseases, such as type 1 diabetes mellitus, celiac disease, and autoimmune thyroid disease." (PMID 36612082, 2022). "Further, it has been established that ICI therapy can induce manifestations of celiac disease in genetically at-risk individuals, as described in a recent case report of diet-responsive celiac disease developing after anti-CTLA-4 therapy." (PMID 35160275, 2022). "For example, CTLA4 and LPP are implicated in both celiac disease and tTGA development, although the association with tTGA appears to be stronger than with celiac disease." (PMID 27015091, 2016). "Conversely, previous reports of an overlap in association between T1D and celiac disease were in regions encoding genes highly expressed in T lymphocytes (RGS1, PTPN2 and CTLA4 in celiac; PTPN2 and CTLA4 in T1D)." (PMID 21852963, 2011). "Multiple population studies have concluded that polymorphism in the CTLA-4 exon is a non-HLA determinant in developing susceptibility to celiac disease." (PMID 39727645, 2024). "Therefore, the importance of CTLA-4 in the control of inflammatory responses in celiac disease is proven." (PMID 38040898, 2023). "Our current results place the candidate genes SH2B3, CTLA4, BACH2 and UBASH3A at the very heart of the immune response in the pathogenesis of both T1D and celiac disease." (PMID 21829393, 2011). "As previously discussed, CTLA-4 is also known to influence T-cell activation and thus is thought to be a non-HLA gene contributor to celiac disease and is the target for ipilimumab." (PMID 39727645, 2024). "Lastly, four of the nine TPOA associated SNPs (in SH2B3, CTLA4, BACH2 and UBASH3A) have also been associated with celiac disease (but not the SNPs in RASGRP1, STAT4, PTPN22, IL2 and FCRL3)." (PMID 21829393, 2011).
Obesity (21 papers, 2013 to 2025). Accumulation of substantial excess body fat. "CTLA-4 variants are potentially involved in obesity in this cohort of TS patients from northeastern Brazil." (PMID 30508004, 2018). "Data from several studies show that even though obesity causes a state of chronic low-grade inflammation with reductions in effector immune populations, it has a beneficial effect on patient survival following anti-PD-1/PD-L1 and anti-CTLA-4 treatment." (PMID 32422865, 2020). "In addition, an association between the CTLA-4 G/G genotype and obesity was detected in TS patients (p=0.02, OR=6.04)." (PMID 30508004, 2018). "Unlike pembrolizumab, a PD-1 inhibitor that specifically targets the obesity-driven PD-1/PD-L1 pathway, ipilimumab, a CTLA-4 inhibitor, modulates the immune response through a broader mechanism of action." (PMID 40227730, 2025). "In contrast, a murine study looking at the effects of obesity on anti-CTLA-4 treatment of adenocarcinoma found reduced efficacy in obese BALB/c mice." (PMID 32422865, 2020). "Moreover, obesity promotes the recruitment of MDSCs, which in turn upregulate the expression of CTLA‐4 and PD‐L1, thereby suppressing T‐cell‐mediated antitumor immunity." (PMID 41267926, 2025). "Bifidobacterium pseudolongum enhances antitumor immunity, exerts an anti-influenza effect, enhances the efficacy of anti-CTLA4 treatment (Research, A. A for C. 2020), and treated obesity in an animal model, which inspired us to explore its mechanism from the perspectives of immunity and metabolism." (PMID 34490139, 2021). "Furthermore, only patients with overweight or obesity who received combination ICIs (i.e., anti-CTLA-4 + anti-PD-1) had a statistically significant improvement in PFS (p = 0.0044) and trended toward improved OS (p = 0.47)." (PMID 34421889, 2021). "Fewer studies have looked at the effect of obesity on anti-CTLA-4 treatment." (PMID 32422865, 2020). "Several authors reported that, although obesity may induce a state of chronic low-grade inflammation which may impair effector immune populations, it may also correlate with improved benefit on patient survival following anti-PD-1 or anti-CTLA-4 treatment." (PMID 35565422, 2022). "PD-1, like CTLA-4, is a senescence marker of T cells, and PD-1+ T cells accumulate in WAT in high-fat diet-induced obesity." (PMID 38551005, 2024). "Thus, a key challenge in immunotherapy is to augment anti-tumor immunity without exacerbating the pro-tumorigenic obesity-associated inflammation, which may require different approaches for the same target for CTLA-4." (PMID 31475003, 2019). "A number of host factors including SNPs of interferons IL28A, IL28B, IL29, interferon-γ, MBL, IL -10, IL-18, CTLA4, TRAIL, TGF-β, MX1, Osteopontin, LMP7, OAS1 genes, insulin resistance, obesity and ethnicity, have been found to modulate the treatment response." (PMID 24079723, 2013). "However, the absence of PD-1 and CTLA-4 upregulation on iNKT cells from individuals with obesity argues against a classical exhaustion phenotype." (PMID 41000378, 2025).
thyroid cancer (21 papers, 2018 to 2026). "Tregs (CD4+CD25hiCD127lo) inhibit the anti-tumor response by producing IL-10 and expressing immune checkpoints CTLA-4 and PD-1, hence higher number of these cells in the circulation is associated with more aggressive thyroid cancer." (PMID 38235146, 2023). "Future directions for CTLA-4-and PD-1/PD-L1-based immunotherapy in thyroid carcinoma, including combination therapy and individualised treatment, and understanding the complex mechanisms of combined therapy will continue to be explored." (PMID 39286684, 2024). "The prognostic role of CTLA-4 in thyroid carcinoma is still controversial and under evaluation, while in NSCLC, its expression was found to be related to decreased death rates." (PMID 39286684, 2024). "Among them, there were 7 mutation sites of importance for HT-related genes [CTLA4 (1 site), BACH2 (3 sites), and RNASET2 (3 sites)] where at least two patients with thyroid cancer experienced mutations." (PMID 34993154, 2021). "The only clinical trial exclusively considering thyroid cancer is investigating a combination of a PD-L1 and a CTLA-4 inhibitor." (PMID 34258030, 2021). "At the time of writing, there were 60 ongoing clinical trials considering CTLA-4 inhibitors in solid tumors, two of which specifically listed thyroid cancers." (PMID 34258030, 2021). "Immunotherapy is also under research, but the efficacy of PD-1/PDL-1 or CTLA-4 inhibitors in all thyroid cancer subtypes is different and novel strategies in the immune cell cycle are needed to achieve better responses." (PMID 32668761, 2020). "The use of immune checkpoint inhibitors, such as anti-CTLA-4, anti-PD-1, and anti-PD-L1 antibodies, allows the reactivation of an adaptive anti-tumor immune reaction and opens the development and clinical validation of immunotherapy in thyroid cancer." (PMID 40965626, 2025). "Among them, the combination of ICB and TKI, such as some fixed treatment modes such as Cabozantinib and Atezolizumab(PD-L1), Cabozantinib and Nivolumab(PD-1) and Ipilimumab(CTLA-4), Lenvatinib and Pembrolizumab(PD-1) are still feasible ideas for the treatment of thyroid cancer." (PMID 38403820, 2024). "An increased expression of CTLA-4 in TILs has been observed, and its coexpression with PD-L1 in tumours might have a prognostic role in thyroid carcinoma; hence, more studies emphasising the correlation might be required to establish the prognostic role." (PMID 39286684, 2024). "This is the first study on CTLA-4 expression by IHC in tumour and ICs in thyroid carcinoma." (PMID 39286684, 2024). "The phase II, single-arm, multi-cohort GETNE-DUTHY trial (clinicaltrials.gov NCT03753919, EudraCT 2018-001066-42) aimed to determine whether dual anti-PD-L1/CTLA-4 inhibition using durvalumab and tremelimumab can improve the clinical outcomes in advanced thyroid cancer." (PMID 41935063, 2026). "The relationship between m6A score and Tumor Mutation Burden (TMB) and its correlation with the expression of PD-1 antibody and CTLA4 antibody proved that m6A score could be used as a potential predictor of the efficacy of immunotherapy in thyroid cancer patients." (PMID 36791151, 2023). "Besides, thyroid cancer cells upregulated negative immune checkpoints, such as CTLA-4 (cytotoxic T-lymphocyte associated protein 4) and PD-L1 (programmed death-ligand 1), as well as immunosuppressive enzymes (IDO1, indoleamine 2,3-dioxygenase 1)." (PMID 37434155, 2023). "Our research group used bioinformatics to analyze the Oncomine database and found that HT-related genes (TSHR, BACH2, RNASET2, CTLA4, PTPN22, IL2RA) were expressed in different types of thyroid cancer." (PMID 34993154, 2021). "Among them, TSHR and RNASET2 were highly expressed in malignant tumors, especially TSHR in thyroid cancer, while BACH2, CTLA4, PTPN22, IL2RA, and other immune-related genes are expressed significantly lower in thyroid cancer." (PMID 34993154, 2021).
thyroid cancer (continued). "In thyroid carcinoma, the correlation between OS and CTLA-4 needs to be explored, and studies with larger cohorts need to be conducted to understand the prognostic role of CTLA-4." (PMID 39286684, 2024). "Furthermore, it has been demonstrated that thyroid CAFs increase the expression of various immune checkpoints, such as CTLA4, PDL1/2 and IDO 1, and thus contribute to the immune escape of thyroid cancer cells and consequently to thyroid tumor growth." (PMID 36077709, 2022). "A literature search did not identify any preclinical studies involving CTLA-4 inhibitors on thyroid cancer tissue or cells." (PMID 34258030, 2021). "However, PD-1, PD-L1 or CTLA-4 in human clinical thyroid tumors are not prognostic for thyroid cancer outcomes." (PMID 40075642, 2025). "CTLA-4 immunoexpression in thyroid carcinoma has not been studied." (PMID 39286684, 2024).